PEBP1P3 (phosphatidylethanolamine binding protein 1 pseudogene 3)
Gene: Processed pseudogene on chromosome 1 (198,679,139 to 198,680,033, reverse strand). Ensembl gene ENSG00000236278.
Diseases named in the same sentence as PEBP1P3 in open-access papers:
PEBP1P3 is named in the same sentence as 1 disease in open-access papers, as found by Europe PMC text mining. Sharing a sentence is not in itself a finding about the gene and the disease.
PEBP1P3 shares sentences with these, for which no sentence is quoted: asthma (1 paper).